APOE (apolipoprotein E)
Diseases named in the same sentence as APOE in open-access papers (continued):
Sharing a sentence is not in itself a finding about the gene and the disease.
atherosclerosis (continued). "Consequently, enhanced CD68-expressing foam cells and increased M1 polarization was found in the plaque content of atherosclerosis-prone ApoE−/− mice." (PMID 35087883, 2021). "The present study was designed to determine the impact of FA on atherosclerosis in ApoE−/− mice." (PMID 33841148, 2021). "Apolipoprotein E (ApoE) is a lipoprotein involved in the catabolism of triglcyeride-rich lipoproteins, and ApoE−/− mice were used to better detect plaque formation as ApoE is known to suppress atherosclerosis." (PMID 34638614, 2021). "The COX-2 inhibitor MF-tricyclic increased the early atherosclerosis lesion area in apoE-/- mice." (PMID 34592918, 2021). "Using streptozotocin (STZ)-induced diabetic ApoE−/− mice, we found that metformin reduces atherosclerotic plaques, while S177A-Pdlim5, an unphosphorylatable mutant that carried adenovirus, undermines metformin's anti-atherosclerosis function." (PMID 34368251, 2021). "There are several mouse models of elevated non-HDL cholesterol that drive atherosclerosis in large arteries, including apoE-deficient, LDL-receptor deficient, LDL-receptor knockdown, and apoB-transgenic." (PMID 35052410, 2021). "An atherosclerosis animal model, established by placing a perivascular collar on the right common carotid artery in ApoE−/− mice, was used to investigate whether TGF-β is the key molecular mediator of SL in crosstalk between macrophage and SMC." (PMID 34122091, 2021). "Moreover, in ApoE−/− knockout mice, an animal model of hyperlipidemia and atherosclerosis, it was shown that chronic oxytocin treatment attenuated aortic atherosclerosis in a site-specific manner." (PMID 34638587, 2021). "Consistent with the robust Il-10 induction in the plaque, exosome-based delivery of the engineered Il-10 could alleviate the atherosclerosis in ApoE-/- mice." (PMID 34815799, 2021). "In addition, the enhancement of miR-146a levels in monocytes and macrophages by cellular apoE suppresses NF-κB-mediated inflammation and atherosclerosis." (PMID 33669374, 2021). "In apolipoprotein E (apoE)-deficient mice, inhibition of EV-mediated miR-155 transfer from SMC to endothelial cells, using anti-miR-155, reduced the endothelial injury and atherosclerosis, suggesting a promising therapy for atherosclerotic patients." (PMID 33808038, 2021). "ApoE-/- mice were fed a Western diet for 12 weeks to induce atherosclerosis." (PMID 33436015, 2021). "In addition, the induction of HSPs before the formation of atheromas, inhibited the progression of atherosclerosis in ApoE−/− mice." (PMID 33782520, 2021). "However, the knockdown of lncRNA H19 served as a protection against atherosclerosis in apoE−/− mice and lowered the accumulation of lipids in ox-LDL-induced THP-1 macrophages." (PMID 34820432, 2021). "Furthermore, it decreased plasma cholesterol concentration and inhibited atherosclerosis in apoE-null mice." (PMID 33800446, 2021). "The apolipoprotein E-knockout mouse is a widely used animal model to study the genetics and pathogenesis of atherosclerosis, since spontaneously develop the morphological changes, as well as the oxidative and molecular modifications that characterize the disease in humans within 6–10 weeks." (PMID 34206655, 2021). "Importantly, nicotine-induced NLRP3 inflammasome activation and macrophage migration into atherosclerotic plaque were reversed by methyl-β-cyclodextrin, making a significant improvement for atherosclerosis in apoE–/– mice fed with a high-fat diet." (PMID 34490270, 2021). "The ApoE−/− mouse is the most commonly used animal model for studying atherosclerosis." (PMID 34594369, 2021). "We confirmed that DLTs indeed ameliorated atherosclerosis in ApoE−/− mice." (PMID 34566648, 2021). "Consistent with the robust Il-10 mRNA induction in the plaque, exosome-based delivery of the engineered Il-10 mRNA could alleviate the atherosclerosis in ApoE-/- mice." (PMID 34815799, 2021).
atherosclerosis (continued). "Indeed, in atherosclerosis prone, VCAM1-deficient mice (ApoE−/−;VCAM1D4D/D4D), fatty streak formation and atherogenesis is blunted when compared to atherosclerosis-prone mice that do express VCAM1 (ApoE−/−VCAM1+/+ mice)." (PMID 33562658, 2021). "Besides, the EPCs were isolated from ApoE gene to knockout rat bone marrow for closer to the pathological model of atherosclerosis in CHD, which was better than before in study protocol." (PMID 34708093, 2021). "Numerous studies have shown minimal expression of Cyr61 in normal arteries but markedly increased expression at sites of atherosclerosis or vascular injury including carotid endarterectomy specimens, aorta in older ApoE−/− mice, and at sites of mechanical or drug-induced vascular injury." (PMID 33574403, 2021). "As ApoE isoforms play different roles in the onset and development of atherosclerosis and AD, with lipids found in both atherosclerotic and AD plaques, we therefore used NR to determine how the nascent-like rHDL of each isoform behave in the exchange or removal of lipids." (PMID 33996741, 2021). "Taken together, we found that AceK augmented HCD-induced dyslipidemia through an increment in lipogenesis and decrement in lipolysis, and these effects might further exacerbate HCD-induced atherosclerosis in ApoE−/− mice." (PMID 34836239, 2021). "CKD induced by 5/6 nephrectomy (5/6Nx) has been shown to increase atherosclerosis in apoE KO mice." (PMID 33436815, 2021). "ApoE function is important for the clearance of atherogenic lipoprotein remnants via binding to LDL receptors on the liver, thereby decreasing the risk of atherosclerosis and other CVD complications." (PMID 33925808, 2021). "Therefore, we assessed the effect of PEA-15 ablation on lipid plaque development in the Apolipoprotein E (ApoE)-null model of atherosclerosis." (PMID 33772049, 2021). "hApoE2 and ApoE KO rats developed only mild atherosclerosis." (PMID 34361033, 2021). "ApoE−/− mice are a practical model of hyperlipidemia and atherosclerosis." (PMID 33652838, 2021). "Considering the anti-angiogenic role of Rb1, average number of vasa vasorum in adventitia surrounding the atherosclerosis plaques in aortic roots were counted to uncover whether Rb1 could inhibit neovascularization in apoE−/− mice." (PMID 34124194, 2021). "The goal of this study is to investigate whether acacetin can protect against oxidative stress in humans and attenuate atherosclerosis in apoE−/− mice." (PMID 33241629, 2021). "Finally, to determine the role of CTRP12 in atherosclerosis in vivo, apoE−/− mice were fed a ﻿Western diet for 12 weeks and simultaneously injected with PBS, LV-NC or LV- CTRP12." (PMID 33692340, 2021). "ApoE−/− mice display poor lipoprotein clearance and elevated levels of plasma cholesteryl ester-enriched lipoprotein particles, thereby promoting the development of atherosclerosis." (PMID 34297054, 2021). "RVX-208 has been shown to inhibit the development of atherosclerosis in ApoE−/− mice." (PMID 34940525, 2021). "Overall, the appropriate usage of these redox ratios of apoE according to the apoE phenotype could allow for the detection of atherosclerosis and its related pathological conditions, such as insulin resistance and dyslipidemia." (PMID 34286848, 2021).
atherosclerosis (continued). "Because most of the recent studies in regard to the role of Th17 cells are focused on the advanced stage of atherosclerosis, we also detect the infiltration of Th17 cells in ApoE−/− mice fed with HFD at different time points (i.e., 8, 12, 16, and 20 weeks after HFD)." (PMID 33981738, 2021). "Moreover, liposomes containing the anionic phospholipid 1,2-distearoyl-sn-glycero-3-phosphoglycerol induced Treg proliferation and reduced atherosclerotic plaque formation in apolipoprotein E (ApoE−/−) mice, a model of atherosclerosis." (PMID 34198865, 2021). "The results suggested that amygdalin could attenuate atherosclerosis and play an anti-inflammatory role via MAPKs, AP-1 and NF-κB p65 signaling pathways in ApoE−/− mice and oxLDL-treated bone marrow-derived macrophages." (PMID 33192531, 2020). "A report on proteomic analysis of atherosclerosis progression in apoE–/– mice may provide some insight." (PMID 32373127, 2020). "The selective Mas receptor agonist AVE0991 (angiotensin 1-7 mimetic) affected macrophage differentiation and recruitment into the perivascular space, exhibiting anti-inflammatory and antiatherosclerotic actions during the early stages of atherosclerosis in ApoE–/– mice." (PMID 33391033, 2020). "Therefore, in the current study, we used ApoE-knockout mice on a high-fat diet to establish an atherosclerosis model." (PMID 32267831, 2020). "Thus, the exacerbation of atherosclerosis in male ApoE−/− mice housed in constant light occurred independently of systemic metabolic dysfunction caused by obesity." (PMID 32555251, 2020). "Atherosclerosis model was established in vivo in ApoE-/- mice and in vitro in RAW264.7 cells." (PMID 32611832, 2020). "Infusion of Ang II in ApoE−/− mice results in accelerated atherosclerosis." (PMID 32630530, 2020). "In another study in which ApoE*3-Leiden mice were fed a special high-fat and cholesterol diet (15% cacao butter, 0.5% cholate, 1% cholesterol, 40.5% sucrose, 10% corn starch, 1% corn oil, and 4.7% cellulose), extensive atherosclerosis was observed." (PMID 33258000, 2020). "In the current study, we explored whether another immunoproteasome catalytic subunit LMP10 contributed to experimental atherosclerosis in ApoE ko mice." (PMID 33195259, 2020). "Therefore, we investigated the effects of Rg3 on oxidized low-density lipoprotein (ox-LDL) induced human umbilical vein endothelial cells (HUVECs) dysfunction and high-fat diets (HFD) induced atherosclerosis in ApoE−/− mice, as well as the mechanism." (PMID 32390845, 2020). "Recently, using Apolipoprotein null mice (ApoE-/-) on a western diet, a mouse model of nonalcoholic fatty liver disease and atherosclerosis, we further demonstrated the detrimental effects of e-cigarettes albeit at high dosages on the liver as well as on the heart." (PMID 33002059, 2020). "To investigate whether CILP2 was associated with atherosclerosis, we examined the CILP2 expression in the aorta samples and circulating CILP2 levels in ApoE KO mice, a well-characterized animal model of atherosclerosis." (PMID 33204392, 2020). "Additionally, previous metabolomics and transcriptomics-based experiment revealed that LPCs (16:0), (18:0), and (18:1) were significantly elevated in the aortas of apolipoprotein E knockout mice during early atherosclerosis." (PMID 32118038, 2020). "Inhibition of TNF-α reduces atherosclerosis in ApoE−/− mice." (PMID 32635347, 2020). "In this study, we investigated whether continuous artificial light exposure aggravates atherosclerosis by exposing APOE*3-Leiden.CETP mice to either normal LD cycles or LL conditions." (PMID 32915671, 2020). "Genetic deletion of Nox1 in apoE-/- mice led to alleviation of atherosclerosis." (PMID 32245238, 2020).
atherosclerosis (continued). "Apolipoprotein E (ApoE)-knockout (KO) mice are the elective animal model to study atherosclerosis." (PMID 32231663, 2020). "Inhibition of CD40-TRAF6 expression may abolish atherosclerosis and confer plaque fibrosis in ApoE−/− mice by inducing differentiation of macrophages toward a M2 signature." (PMID 32849545, 2020). "Prx1 and Prx2 exacerbate atherosclerosis on deletion in ApoE mice." (PMID 33014272, 2020). "Systemic anticoagulants can also induce regression of atherosclerosis in ApoE−/− mice." (PMID 32611229, 2020). "Whether HDL that is known to bind SAA can prevent this SAA-stimulated acceleration of atherosclerosis in ApoE−/− mice was the focus of this study." (PMID 32075280, 2020). "The administration of aspirin reduced atherosclerosis in ApoE KO mice." (PMID 32258142, 2020). "Apolipoprotein E deficiency in ApoE–/– mice seems to be strongly correlated with MAFLD development and plays an important role in metabolic syndrome, as the absence of ApoE spontaneously induces hypercholesterolemia, obesity and atherosclerosis." (PMID 33291840, 2020). "By contrast, at an early stage, deletion of the IL6 gene in apoE-deficient mice did not affect the disease relative to control mice, whereas at later stages, this knockout promoted atherosclerosis." (PMID 32121175, 2020). "Also, inhibition of IDO-1 in ApoE−/− mice has been shown to lead to increased vascular inflammation and atherosclerosis." (PMID 33117340, 2020). "In addition, TLR9 gene deletion aggravated the atherosclerosis of ApoE−/− mice fed with high-fat-diet (HFD) and a TLR9 agonist reduced the severity of the disease." (PMID 32002588, 2020). "In an atherosclerosis ApoE−/− mouse model, whole LB consumption upregulated bile acid synthesis gene Cyp7a1, increased the cecal propionic-acid-producing bacteria proportions, and decreased triglyceridemia and atherosclerosis." (PMID 32825710, 2020). "The aim of this study was to investigate whether the natural flavone acacetin could protect against endothelial injury induced by high glucose and attenuate diabetes-accelerated atherosclerosis in streptozotocin-(STZ) induced diabetic ApoE−/− mice model." (PMID 33519472, 2020). "It has been shown that perhexiline, a small drug that is approved for clinical use in many countries except the United States, to treat angina and heart failure, can effectively induce KLF14 expression in the liver while reducing atherosclerosis in ApoE-null mice." (PMID 32548128, 2020). "Compared with sham group, the aortic root of ApoE−/− mice in the UAAS group developed early atherosclerosis, the levels of total cholesterol, triglyceride, low-density lipoprotein-cholesterol, serum creatinine and urea nitrogen were also higher than that in the sham group." (PMID 33276745, 2020). "Indeed, in one study, monomeric CRP, that is also capable of binding to atherogenic LDL, was employed and the results showed that monomeric CRP was protective against atherosclerosis in apoE−/− mice." (PMID 32849641, 2020). "The ApoE−/− mouse is the most widely studied animal model for atherosclerosis." (PMID 31017307, 2020). "Similarly, the impact of preexisting conditions can be investigated using other mouse lines, such as db/db (for type II diabetes) or ApoE-/- (for atherosclerosis)." (PMID 32042333, 2020). "Therefore, in this study, we chose ApoE knockout mice as an atherosclerosis model to investigate the anti-atherosclerosis effects of ISL." (PMID 32328171, 2020).
atherosclerosis (continued). "ApoE–/– is an excellent mouse model of hyperlipidemia and atherosclerosis." (PMID 33490072, 2020). "It is reported that apoE increased expression of miR-146a to suppress NF-κB-driven inflammation and atherosclerosis in macrophages and monocytes, which implies that miR-146a suppresses inflammation during hyperlipidemia to attenuate atherosclerosis." (PMID 32467714, 2020). "In proatherogenic apoE-/- mice, formononetin significantly attenuates atherosclerosis." (PMID 31938053, 2020). "Similarly, dys- or hyper-lipidemia was induced after a long-term exposure of Zinc oxide (ZnO) NPs via intratracheally instillation in rat, or of TiO2 NPs in ICR or ApoE−/− mice, ultimately contributing to the initiation and progression of atherosclerosis." (PMID 33008402, 2020). "Furthermore, the presence of OSM has been detected both in human atherosclerotic lesions and in the mouse ApoE−/− model of atherosclerosis." (PMID 33081064, 2020). "This might be explained by the fact that high-fat induced atherosclerosis in ApoE−/− mice mostly represents a hyperlipidemia-accelerated process when compared to human atherosclerotic conditions." (PMID 33255872, 2020). "The detrimental effects of atherosclerosis on AD were stronger among the APOE ε4 carriers." (PMID 31919381, 2020). "Apolipoprotein E (ApoE)-deficient mice are prone to high-fat diet-induced atherosclerosis, which is reduced in additional TLR4-deficiency or MyD88-deficiency, indicating an important role of TLR4/MyD88 signaling in atherosclerosis." (PMID 32391019, 2020). "In addition, double and triple treatments improve lesion morphology and composition in APOE*3-Leiden.CETP mice with pre-existent atherosclerosis." (PMID 31843957, 2020). "Recent evidence suggested that dietary quercetin may be effective in lowering the risk of atherosclerosis by upregulating PPARγ, LXR-α, and ABCA1 and downregulating CD36 in the liver of apoE-/- mice fed HFD." (PMID 33261070, 2020). "The link between FGFR1 expression and atherosclerosis was further demonstrated in ApoE null mice with endothelial-specific deletion of the FGF receptors signaling scaffold protein fibroblast growth factor receptor substrate 2α (FRS2α), which fully disrupts FGF signaling." (PMID 32478094, 2020). "Carotid PVAT transplantation leads to endothelial dysfunction and accelerated atherosclerosis in ApoE–/– mice, and it could be blocked by neutralization of Psgl-1 (P-selectin glycoprotein ligand-1)." (PMID 33391033, 2020). "We analyzed tissues from ApoE−/− mice at 8 and 20 weeks old because ApoE−/− mice spontaneously develop atherosclerosis at ~12 weeks old, and we could therefore analyze tissue rhythms before and after development of atherosclerosis." (PMID 32555251, 2020). "(TASAES) protected against endothelial cell injury and atherosclerosis in ApoE-/- mice." (PMID 31986489, 2020). "Our previous study indicated that miR-520a-3p was elevated in apoE-/- mice with atherosclerosis." (PMID 33768113, 2020). "One animal model of atherosclerosis includes an apolipoprotein E knockout mouse (ApoE-KO mouse)." (PMID 33308301, 2020). "ApoE KOs animal models are widely used to study experimental atherosclerosis." (PMID 33424633, 2020). "The decrease in chronic inflammation induced by bacterial antigen load might be the underlying pathway of L. mucosae A1 to attenuate hyperlipidemia and atherosclerosis in ApoE-/- mice." (PMID 32806628, 2020). "In this study, we investigated the effect of BBR on atherosclerosis in HFD-fed ApoE–/– mice." (PMID 32231564, 2020). "Similarly, ApoE null mice on high-fat/high-cholesterol diet mice show a progressive increase in EndMT as the extent of atherosclerosis increases." (PMID 32478094, 2020). "Atherosclerosis was induced in apolipoprotein E-knockout (Apoe-/-) mice fed on an atherogenic diet." (PMID 32258175, 2020). "The downregulation of GAS5 prevents atherosclerosis progression in apoE-/- mice." (PMID 33154191, 2020).